FAM41AY1 (family with sequence similarity 41 member A, Y-linked 1)
Synonyms: formerly FAM41AY
Gene: Long non-coding RNA gene on chromosome Y (17,500,958 to 17,515,018, forward strand). Ensembl gene ENSG00000224989.
Homologues: Paralogues in human: FAM41AY2 (100% identical).